PTH (parathyroid hormone)
Diseases named in the same sentence as PTH in open-access papers (continued):
Sharing a sentence is not in itself a finding about the gene and the disease.
vitamin D deficiency (continued). "Body fat mass was inversely related to PTH only in individuals with vitamin D insufficiency." (PMID 38032745, 2024). "For example, individuals with a low VMR (<4%) often have higher PTH levels and markers of bone turnover, indicating functional vitamin D deficiency regardless of serum 25(OH)D concentrations." (PMID 39408192, 2024). "In our study cohort, 70.9% of the patients had vitamin D insufficiency, which did not affect the risk of fractures but did not cause an increase in parathyroid hormone, as would be expected physiologically." (PMID 39513358, 2024). "From the responses by the nephrologists, the ideal hypothetical patient profile was 50–77 years old (62.5%), CKD stage 4 (47.0%), vitamin D insufficiency (88.5%), persistently high plasma PTH (83.5%), normal serum Ca (48.5%), normal serum P (51.0%), and no history of CV event or fracture (34.0%)." (PMID 36989323, 2023). "In brief, in a subgroup of Iranian women with significant and often profound vitamin D deficiency evaluated at the start of the third trimester, the shape of the relationship between 25(OH)D and PTH was non-linear and monotonic with a negative slope." (PMID 36721726, 2023). "However, patients with vitamin D insufficiency had a significantly higher percentage of fat mass and PTH concentration than those with vitamin D sufficiency (p = 0.034 and p = 0.027, respectively)." (PMID 36834562, 2023). "In the vitamin D insufficiency group (20 to <30 ng/mL), PTH was high in 25.5% and ALP in 8%." (PMID 36428888, 2022). "Vitamin D deficiency caused a condition of hyperparathyroidism despite having normal calcium levels, demonstrating a relatively narrow range of PTH secretion regulation by extracellular calcium." (PMID 36012852, 2022). "Therefore, the aim of this study was to evaluate the effect of vitamin D deficiency on the RANKL/OPG ratio in the serum blood levels, along with Ca, Pi, and PTH, and to ascertain the association between them." (PMID 35242513, 2022). "Vitamin D insufficiency ranked first with the highest burst strength (10.55), followed by high prevalence (6.63), male (5.18), lactation (5.16), 25 hydroxyvitamin D concentration (4.78), and parathyroid hormone (4.78)." (PMID 36159484, 2022). "However, when postoperative PTH reduction ratio was adopted in the analysis, both 25OHD and vitamin D insufficiency rates were found significantly different between the groups of postoperative PTH reduction ratio ≥50% (ΔPTH50+) and the control group (ΔPTH50−)." (PMID 34956363, 2021). "Also, interventional studies showed a significant PTH decrease with vitamin D supplementation in patients with chronic kidney disease (CKD) and vitamin D deficiency or insufficiency." (PMID 33995282, 2021). "In vitamin D deficiency, higher concentration of PTH is expected, however, not leading to clinical hyperparathyroidism in milder deviations." (PMID 34599252, 2021). "Our study also demonstrated that GFR is a significant predictor of serum PTH even in subjects with normal or near-normal renal function and no vitamin D deficiency." (PMID 33995282, 2021). "In conclusion, our study provided evidence that vitamin D and renal function have additive effects on serum PTH in those without vitamin D deficiency, even at the higher end of the spectrum." (PMID 33995282, 2021). "Moreover, this study revealed that young age, female gender, low albumin level, high PTH level, and high SOFA score are associated with vitamin D deficiency." (PMID 34966771, 2021). "As such, elevated serum PTH levels can be considered a pathognomonic hallmark in the vast majority—but not necessarily all cases—of patients with vitamin D deficiency." (PMID 33553992, 2021). "Age is an independent predictor of PTH only in those without vitamin D deficiency and normal renal function." (PMID 33995282, 2021).
vitamin D deficiency (continued). "If confirmed, future large-scale randomized controlled trials among participants with true vitamin D deficiency are warranted to clarify the preventive dosage of vitamin D supplementation and to address racial differences of CVD risk caused by vitamin D/PTH endocrine dysfunction." (PMID 34531372, 2021). "We showed that declining vitamin D and renal function have additive effects on serum PTH in subjects without vitamin D deficiency." (PMID 33995282, 2021). "The secondary objectives were to compare the level of PTH of patients with EOA with matched controls and to determine the relationship between vitamin D deficiency, PTH level, and pain intensity, disability, psychological, and functional variables in patients with knee EOA." (PMID 34836290, 2021). "In children without vitamin D deficiency, age over 12 years was associated with a 3 pg/mL significant increase in serum PTH after adjusting for serum 25(OH)D." (PMID 33995282, 2021). "After close review of the patient’s medical records by an experienced endocrinologist, the elevated PTH level was determined to be due to an underlying vitamin D insufficiency, rather than to the use of the LED neck device." (PMID 33921839, 2021). "At present, there is no clear conclusion that high levels of PTH are related to obesity or are regulated by vitamin D deficiency and serum calcium." (PMID 34322512, 2021). "Overall, first-trimester vitamin D insufficiency defined as maternal blood levels of 25-hydroxyvitamin D < 30 ng/mL along with levels of PTH above the 80th percentile correlated with prematurity, but the association was not statistically significant (OR = 2.611, 95% CI (0.92, 7.411), p = 0.071)." (PMID 33114615, 2020). "The term CKD-mineral and bone disorder (CKD-MBD) indicates a systemic disorder characterized by abnormal levels of calcium, phosphate, PTH and FGF-23, along with vitamin D deficiency, decreased bone mineral density or altered bone turnover and vascular calcification." (PMID 32486167, 2020). "Subjects with Vitamin D deficiency have significantly high values (p < 0.05) for BMI z-score, waist circumference, waist z-score, body fat percentage, FMI, systolic and diastolic BP, total cholesterol, triglycerides, LDL-C, insulin, HOMA-IR, leptin, and PTH." (PMID 32024097, 2020). "The serum levels of intact parathyroid hormone (iPTH) were higher in vitamin D deficiency patients than those without vitamin D deficiency 450 ± 860 vs. 330 ± 330 pg/mL, p = 0.16), but the difference was not significant." (PMID 32371900, 2020). "A hallmark of vitamin D insufficiency/deficiency is elevated levels of parathyroid hormone and consequently most guidelines on the use of vitamin D in CKD have largely been based on levels of PTH and calcium." (PMID 32180081, 2020). "Women with vitamin D insufficiency, hyperparathyroidism, and PTH below the lower limit." (PMID 33052935, 2020). "Observational studies described that vitamin D deficiency is associated with an increased cardiovascular risk, an increased mortality, irrespective of parathyroid hormone (PTH)." (PMID 33396784, 2020). "Additionally, in this subgroup, 8 individuals also showed slightly higher serum PTH concentrations and 10 patients had a serious vitamin D insufficiency." (PMID 33066259, 2020). "Persistent subnormal 25OHD levels and elevated PTH concentrations may indicate a presurgical presence of both PHP and vitamin D deficiency in this group." (PMID 33210066, 2020). "Calcium, PTH, and 1,25(OH)D were higher (p < 0.001) in individuals with PHP (11.4 ± 0.4, 116 ± 21, 79 ± 6) than in individuals with normal 25OHD (9.6 ± 0.2, 49 ± 5, 57 ± 6) and vitamin D deficiency (9.3 ± 0.2, 62 ± 6, 32 ± 4)." (PMID 33210066, 2020). "Even a slight vitamin D insufficiency is compensated by an increase in serum PTH." (PMID 33184328, 2020). "All the participants with vitamin D insufficiency had normal PTH values." (PMID 32821633, 2020).
vitamin D deficiency (continued). "The overvaluing of 25-OHD measurements without accompanying ALP or PTH measurements and diagnosing ‘vitamin D deficiency’ based on diverse thresholds have resulted in an increased use of high-dose vitamin D." (PMID 31893581, 2020). "It has been suggested that this false negative is due to hypersecretion of PTH as a result of vitamin D deficiency that often co-exists with PHPT, leading to increased tubular resorption and thus reduced urinary excretion of Ca." (PMID 31797261, 2020). "Elevated alkaline phosphatase is thought to be due to development of osteomalacia secondary to reduced conversion of 25- hydroxyvitamin D to its active form i.e. 1, 25- dihydroxyvitamin D in the absence of PTH action and concurrent vitamin D deficiency." (PMID 31856822, 2019). "Vitamin D deficiency increases serum PTH, but most vitamin D–deficient subjects do not have PTH concentrations above the normal range." (PMID 30321335, 2019). "This suggests that clinically important elevations in PTH tend to be observed in vitamin D deficiency rather than vitamin D insufficiency." (PMID 31273631, 2019). "Not all vitamin D deficient patients have high PTH levels, a finding that supports the emerging of new criteria for vitamin D deficiency, diagnosis and treatment, and highlights the importance of PTH test in this regard." (PMID 30723655, 2018). "In a small population sample of 14 newly transplanted patients with vitamin D insufficiency, treated with cholecalciferol 400 IU daily plus calcium, 25-OH-D increased significantly, with PTH levels being decreased by half at the end of the 12-month study period." (PMID 28726185, 2018). "As the rate of vitamin D deficiency decreases in the early years due to vitamin D supplementation, the recommendation should be set due to a clinical threshold level of 30 ng/ml for 25-OHD based on PTH levels in children of our population." (PMID 29562938, 2018). "Vitamin D deficiency is common throughout the world, but not all vitamin D deficiencies are accompanied by a rise in parathyroid hormone (PTH)." (PMID 30723655, 2018). "The objective of the present study was to evaluate the relationship between hyperbilirubinemia and serum vitamin D levels –not to assess the etiology of vitamin D deficiency; as a result, PTH, TSH and free T4 were not measured in this study." (PMID 29803223, 2018). "All of the healthy subjects with vitamin D insufficiency showed normal PTH concentration." (PMID 30723655, 2018). "All healthy subjects with vitamin D insufficiency showed normal PTH concentration." (PMID 30723655, 2018). "vitamin D deficiency leads to hyperactivity of parathyroid gland to compensate for lack of vitamin D, as the result of which PTH level increases." (PMID 30093913, 2018). "Furthermore, secondary hyperparathyroidism is a well-known consequence of vitamin D insufficiency and increased PTH levels promote calcium influx into the adipocytes." (PMID 28686645, 2017). "In the present study, the mean preoperative PTH was similar in both the groups (58.85±24.98 in patients with vitamin D deficiency and 56.93±29.18 in the group without vitamin D deficiency; P=0.76)." (PMID 28955671, 2017). "Mean (SD) postoperative PTH in patients with and without vitamin D deficiency were 23.49 (17.96) and 17.77 (15.48), respectively (P=0.13)." (PMID 28955671, 2017). "The mean values of PTH were not statistically different between severe vitamin D deficiency and vitamin D insufficiency subjects." (PMID 28124221, 2017). "When PTH levels were compared in the three groups, ANOVA showed that mean values of PTH levels were significantly lower in subjects with vitamin D sufficiency (p < 0.0001) compared to vitamin D insufficiency or severe vitamin D deficiency subjects." (PMID 28124221, 2017). "PTH was elevated in 22% of the subjects with vitamin D deficiency, in 5% of those with insufficiency and in none of the ones with sufficiency, p < 0.001." (PMID 26910625, 2016).
vitamin D deficiency (continued). "In the present series of young CHD patients, we failed in detecting such a relationship between 25OHD and NT-proBNP levels as well as between PTH and NT-proBNP levels, though in the present young CHD cohort vitamin D deficiency and mild hyperparathyroidism frequently occurred." (PMID 26955207, 2016). "Nine participants with vitamin D-deficiency had increased serum-parathyroid hormone, however none of those had aberrations in plasma-calcium." (PMID 26694031, 2015). "In fact, vitamin D insufficiency and PTH over the 65 ng/l, this may be a threshold for initiating the optimal replacement therapy." (PMID 31105806, 2015). "Recent reports, however, suggest that EPO resistance to high PTH levels is probably related to vitamin D deficiency, whose levels were not assessed in previous studies." (PMID 25781618, 2015). "In mice with targeted deletion of the Gc gene that completely lack DBP, PTH levels were not different between controls and animals without vitamin D toxicity or prolonged vitamin D deficiency (25OHD ≤6 ng/ml [15 nmol/l])." (PMID 25350643, 2014). "The cut-off that defines vitamin D insufficiency is based on a threshold for serum 25(OH)D above which there is no further suppression of parathyroid hormone (PTH) to reduce bone loss." (PMID 24992199, 2014). "Furthermore, intravenous magnesium infusion led to a significant rise in PTH in the group with functional hypoparathyroidism and a reduction in PTH in the subjects with vitamin D insufficiency." (PMID 23981518, 2013). "Under physiologic conditions, serum PTH concentrations tend to correlate negatively with serum 25(OH)D concentration in case of severe vitamin D deficiency, but no such correlation was found in our study, a finding which has been also reported by others." (PMID 23372745, 2013). "Fibroblast growth factor 23 (FGF23) is a recently discovered 30 kDa bone-derived circulating hormone that plays an important role in the complex and tightly regulated mechanism of mineral metabolism, including hyperphosphatemia, vitamin D insufficiency, and elevated parathyroid hormone (PTH) levels." (PMID 24015259, 2013). "In nonpregnant adolescents and adults, increased PTH is associated with lower circulating concentrations of ionized calcium, which is most often precipitated by vitamin D deficiency and decreased intestinal calcium absorption." (PMID 22666547, 2012). "This syndrome comprises vitamin D deficiency, vascular calcification, abnormalities in bone turnover, altered metabolism of calcium and phosphate, and increased levels of fibroblast growth factor-23 (FGF-23) and parathyroid hormone (PTH), known as secondary hyperparathyroidism (SHPT)." (PMID 40525801, 2025). "An inflection point in the nonlinear 25(OH)D–PTH relationship, referred to as a PTH suppression point, may identify a 25(OH)D threshold below which subclinical vitamin D deficiency (lower 25(OH)D) most potently contributes to suboptimal bone mineralization." (PMID 40139482, 2025). "Given the fact that nutritional rickets, hypocalcaemia and SHPT have all been associated with heart failure, this PTH-mediated pathway could explain the negative cardiovascular effects of vitamin D deficiency, aside from VDR activation." (PMID 38541146, 2024). "Our results show that in all age groups, vitamin D deficiency was related to a higher risk of DSPN and this relationship was independent of sex, age, weight, blood pressure, HbA1c, T2DM duration, calcium, phosphorus, parathyroid hormone, lipids and renal function." (PMID 38590822, 2024). "Vitamin D deficiency may exacerbate the PTH-phosphate correlation, as it disrupts the negative correlation between PTH and vitamin D, leading to a stronger positive correlation between PTH and phosphate levels." (PMID 39040613, 2024).
vitamin D deficiency (continued). "Additionally, we neither assessed other vitamin-D-associated biochemical parameters, such as parathyroid hormone (PTH), serum calcium, or phosphate, nor the functional parameters of vitamin D deficiency, as these were out of the scope of this study." (PMID 37111224, 2023). "Elevated PTH but not vitamin D deficiency has been associated with increased risk of heart failure." (PMID 36145186, 2022). "In compliance with several studies, we found a negative correlation between the concentrations of PTH and 25(OH)D, and several authors have suggested that vitamin D deficiency could contribute through hyperparathyroidism secondary to accelerated bone turnover." (PMID 35750999, 2022). "Vitamin D deficiency in CKD directly impacts the homeostasis of calcium and phosphate: under physiological conditions, regulatory feedback loops maintain this homeostasis, with vitamin D, the fibroblast growth factor-23 (FGF23), and the parathyroid hormone (PTH) acting as additional regulators." (PMID 35893866, 2022). "Prepubertal patients with GH deficient do not appear to have a higher risk of vitamin D deficiency than healthy subjects, and with treatment with rhGH, no changes in the organic content of vitamin D were observed although a significant increase in PTH levels was detected." (PMID 35626902, 2022). "The study did not assess parathyroid hormone and bone profile (calcium, phosphate, and alkaline phosphates) to exclude secondary hyperparathyroidism, although other secondary causes of vitamin D deficiency (e.g., chronic kidney disease, liver disease, and malabsorption) were excluded." (PMID 35167624, 2022). "Also, in children with normal renal function and no vitamin D deficiency, increasing age was associated with higher serum PTH after adjusting of 25(OH)D levels." (PMID 33995282, 2021). "In fact, elevated PTH values could be considered an indicator of vitamin D insufficiency." (PMID 33924215, 2021). "Of note, not all those with vitamin D deficiency had increased PTH, which may suggest regulation by unknown factors or that current laboratory normal range for PTH is overestimated for patients with obesity." (PMID 34322512, 2021). "As a consequence of relatively more vitamin D deficiency in obese women, the mean PTH concentration was significantly higher than in nonobese women (20.8 ± 15.9 versus 17.1 ± 12.7, respectively, P = 0.0034), but the mean serum calcium level was comparable in both groups." (PMID 34950730, 2021). "However, vitamin D insufficiency is an independent predictor of postoperative PTH reduction ratio." (PMID 34956363, 2021). "However, in CKD, the recommendations of the KDIGO guidelines to correct vitamin D deficiency prior to initiating therapy with calcitriol often fails to correct serum PTH." (PMID 34950686, 2021). "Our study analyzed the combined effects of vitamin D status and renal function on serum PTH across the whole range of clinically encountered scenarios, from subjects with normal GFR and vitamin D sufficiency to those with severely impaired renal function and vitamin D deficiency." (PMID 33995282, 2021). "However, in that study perioperative PTH levels and vitamin D deficiency were not measured and different thyroid diseases (thyroid cancer, graves' disease and nodular goiter) were included." (PMID 35071309, 2021). "However, normative PTH values are lacking in the Middle-East, more particularly in Lebanon, a part of the world known for its high prevalence of vitamin D deficiency." (PMID 32148490, 2020). "In the meantime, chronically elevated serum PTH secondary to vitamin D insufficiency may stimulate bone turnover, causing negative bone balance and increased risks for low BMD and bone fracture." (PMID 33126597, 2020). "Moreover, all (100%) patients with vitamin D insufficiency also reported normal serum PTH levels." (PMID 32821633, 2020).